INS (insulin)
Diseases named in the same sentence as INS in open-access papers (continued):
Sharing a sentence is not in itself a finding about the gene and the disease.
diabetes (continued). "One of the most common chronic diseases is diabetes, which occurs either when the pancreas does not produce enough insulin or when the body cannot effectively use the insulin it produces." (PMID 28117682, 2017). "The variable “diabetes mellitus” was not put into the model due to its interaction with variable “insulin”." (PMID 28794518, 2017). "Development of diabetes is mainly attributed to the lack of insulin-producing β-cells (type 1 diabetes, T1D) or as a result of insulin resistance (type 2 diabetes, T2D) that eventually leads to β-cell dysfunction or failure." (PMID 28801559, 2017). "Based on previous studies, we hypothesized that patients with type 2 diabetes mellitus would show a correlation between AGE content and both insulin secretion ability and insulin resistance." (PMID 28695132, 2017). "Diabetic subjects who were administered just metformin (n = 20) had lower insulin, glucose, and HOMA-IR levels compared to subjects who received insulin plus metformin (n = 10) or no diabetes medication (n = 3)." (PMID 28947922, 2017). "In diabetes rat model established by high fat diet/low dose streptozotocin, CMD-05 inhibited DPP-IV activity, significantly improved glucose tolerance, increased GLP-1 and insulin levels in plasma." (PMID 28406239, 2017). "It is characterized by long-lasting hyperglycemia, due to lack of pancreatic insulin secretion (type 1 diabetes mellitus) and/or insulin resistance in peripheral organs (type 2 diabetes mellitus)." (PMID 28854935, 2017). "Twenty percent filled insulin prescriptions, and 44.4% filled no prescriptions for diabetes medicines." (PMID 28799214, 2017). "Consistently, serum insulin levels of patient 2 and patient 3 in our study were high, but they had not developed diabetes so far." (PMID 27612026, 2017). "In response to lack of glucose availability in cells during diabetes (insufficiency or insensitivity of insulin), the organ accommodates the breakdown of glycogen to release glucose through glycogenolysis." (PMID 29216879, 2017). "Type 1 diabetes is characterized by a lack of insulin production and requires daily administration of insulin; type 2 diabetes mellitus (T2DM) is characterized by high blood glucose levels and, a relative lack of insulin." (PMID 29201589, 2017). "Immunization with the multi-epitope vaccine in streptozotocin-induced diabetes C57BL/6J mice successfully induced specific anti-URAT1 antibody, which inhibited URAT1 action and uric acid reabsorption, and increased pancreatic insulin level with a lower insulitis incidence." (PMID 29035321, 2017). "It has been proposed that pathologic muscle lipid, such as that which accumulates in the setting of obesity or diabetes, contains lipotoxic intermediates, and it is these, rather than the absolute presence of lipid, which mediate insulin resistance." (PMID 27445983, 2016). "It is hence concluded that there is no proof to support the use of T. crispa 3 g a day for additional therapy in patients with type 2 diabetes mellitus that refused insulin injection and did not respond to oral hypoglycemic drugs." (PMID 27047378, 2016). "She began subcutaneous insulin injection therapy for her diabetes mellitus on day 3 and did not resume taking vildagliptin." (PMID 27520566, 2016). "Given their central role in insulin signalling, it is perhaps not surprising that abundant evidence exists to show that IRS proteins are implicated in vascular complications of diabetes." (PMID 27514532, 2016). "Diabetes mellitus is a chronic disease in which the body does not produce enough insulin to function properly (type 1) or body cells do not react to insulin (insulin resistance) (type 2)." (PMID 27071614, 2016). "For example, a few participants with diabetes explicitly stated that they had sought to achieve ‘perfect control’ of their condition through close adherence to their insulin regime, but none claimed to have actually achieved this goal for very long." (PMID 26140336, 2016).
diabetes (continued). "Administration of insulin reduced serine 262 phosphorylation in these animals, suggesting that the increase was due to the hypoinsulinemia of diabetes and not an effect of the streptozotocin (left)." (PMID 27034963, 2016). "The following factors were considered: age, family history of diabetes, education, pre-pregnancy BMI, OGTT 0 h, OGTT 1 h, OGTT 2 h, fasting C-peptide, postprandial C-peptide, SBP, DBP, TG, LDL-C, HDL-C, HbA1C, insulin medication, and mode of blood glucose monitoring." (PMID 26814139, 2016). "Insulin administration does not prevent long-term complications of diabetes, because an optimal insulin dosage is difficult to maintain." (PMID 26862531, 2016). "According to the World Health Organization (WHO), diabetes is a chronic disease that occurs when the pancreas does not produce enough insulin or when the body cannot effectively use the insulin." (PMID 27769953, 2016). "Insulin sensitivity is usually related to body mass index (BMI), and the highest BMI in this study was found in patients with ACS and diabetes, which might have influenced the microcirculation in these patients." (PMID 27095564, 2016). "Diabetes mellitus (DM) is a group of metabolic diseases of prolonged hyperglycaemia due to either the pancreas not producing enough insulin, or the cells of the body not responding properly to the insulin produced." (PMID 26798654, 2016). "Torrens and colleagues assessed insulin sensitivity and β cell function in non-diabetes premenopausal or early peri-menopausal non-Hispanic white women, as well as in African American, Chinese American, Japanese American, and non-Mexican-American Latino women." (PMID 27830830, 2016). "In this study, we found that when given in conjunction with aCD3, OFS improves the aCD3-mediated diabetes reversal rate in NOD mice, accompanied by an improvement in insulin sensitivity, a reduction in insulitis, and an increase in beta-cell proliferation rate and insulin secretion." (PMID 27874076, 2016). "An earlier systematic review reported that there was low-quality evidence to indicate that a low AGE diet is beneficial for improving insulin sensitivity in patients with diabetes, yet recent research included in this review does not support this idea." (PMID 26938557, 2016). "The mechanisms of how resveratrol influences glucose control and insulin sensitivity in participants who do not have diabetes are unclear." (PMID 26840331, 2016). "Decreases is insulin sensitivity and insulin secretion were largest for BMI and waist circumference suggesting that these two obesity markers in the FINRISC are likely to be the most important drivers for the conversion to diabetes." (PMID 27851812, 2016). "The diabetes protocol used was established considering the animals lost around 10% of their body weight and they would not survive for longer period without insulin administration." (PMID 27764229, 2016). "The present study examined hypoglycaemia prevalence and rates in a large global cohort of insulin‐treated patients with diabetes, including many countries and several regions with no previously published data." (PMID 27161418, 2016). "The course and mortality of sepsis was similar in patients with diabetes mellitus who were and were not on chronic insulin therapy." (PMID 27495247, 2016). "To date, no study has detailed insulin sensitivity in Chinese subjects with newly presented type 2 diabetes mellitus stratified by A1c levels." (PMID 26640807, 2016). "The current study revealed that serum OPN levels directly correlate with several cardio-metabolic risk factors, such as higher BMI, SBP, DBP, lower HDL, diagnosis of T1DM, but not with insulin dose, diabetes duration, and HbA1c." (PMID 27353561, 2016). "Diabetes is a chronic disease that occurs either when the pancreas does not produce enough insulin or when the body cannot effectively use the insulin produced by the pancreas." (PMID 27257845, 2016).
diabetes (continued). "Type-2 diabetes is the most common type of diabetes, which the body is able to produce insulin but either this is not sufficient or the body is unable to respond to its effects, leading to a build-up of glucose in the blood." (PMID 26808535, 2016). "In that study of pancreata from lean or obese people with or without diabetes, relative pancreatic β cell volume of diabetic individuals (i.e., insulin dependent) was approximately 50 % of their non-diabetic counterparts." (PMID 26370678, 2016). "Second, the dawn phenomenon, defined as an early morning rise in blood glucose levels and/or insulin requirements without food intake, was observed in patients with diabetes mellitus, as well as in healthy individuals." (PMID 27834901, 2016). "Type 1 diabetes mellitus (DM1) appears in childhood and early adulthood demanding daily insulin injections for life, while type 2 diabetes mellitus (DM2) appears later in life, in mid-adulthood, demanding diet and lifestyle modifications, oral medication or insulin injections." (PMID 27453739, 2016). "Although exogenous administration of insulin is an effective treatment for acute hyperglycemia in type 1 diabetes mellitus, it does not prevent secondary complications and can, in some cases, lead to hypoglycemia." (PMID 27284233, 2016). "Though the exact links between diabetes and cancer are not known, the exposure to hyperglycemia, elevated insulin, and growth-promoting IGF-1 have been postulated to be the possible reasons explaining the increased incidence of cancers in diabetic patients." (PMID 27512375, 2016). "Patients were excluded if they had non-specific diagnosis codes and were prescribed insulin as their first-ever treatment for diabetes." (PMID 27861488, 2016). "A greater percentage of patients in the OPDP cohort were on an insulin and non-insulin diabetes therapy regimen (OPDP, 15.4 %; PDP, 8.6 %)." (PMID 26972690, 2016). "This was a single-centered study and diabetes was diagnosed at admission according to prior history but not by glucose or insulin level tests." (PMID 27537568, 2016). "For a person with diabetes, the pancreas fails to make sufficient insulin, improperly uses the insulin, or both." (PMID 27535125, 2016). "The association between tobacco use, IR (fasting plasma glucose, insulin, and the homeostatic model assessment of insulin resistance (HOMA-IR)) and incident diabetes over 10 years was evaluated using multivariable linear regression and Cox proportional hazards models, respectively." (PMID 27322410, 2016). "Our results show that in early stage diabetes (ET2D), where insulin secretion from pancreas is significantly low, CSE performs better than metformin or aspirin in normalizing blood sugar; and better than metformin and as good as aspirin in reducing inflammation." (PMID 26877773, 2016). "Across a random 0.5 % sampling of each cohort, multivariable-adjusted differences between the diabetes therapy classifications (insulin alone, insulin + non-insulin (both), non-insulin, and none) were statistically significant (P < 0.0001 for both cohorts)." (PMID 26972690, 2016). "Activation of the Notch pathway in obesity results in heightened diabetes and fatty liver production, as a consequence of an augmented lipogenesis that is not blocked despite the reduced insulin signaling." (PMID 27551310, 2016). "Longitudinal studies show that individuals who progressed to diabetes did not have compensatory increases in insulin secretion; in contrast, those that did, did not progress." (PMID 27048248, 2016). "Relative to patients with diabetes mellitus who were not on chronic insulin therapy, patients treated with insulin were younger, less frequently male and had less cardiovascular insufficiency, less malignancy, and more renal insufficiency." (PMID 27495247, 2016). "In other words, central insulin action was impaired although none of these 6 depressive patients were diagnosed with diabetes." (PMID 27274905, 2016).
diabetes (continued). "A study conducted in Mekelle Ethiopia has also identified that scattered populations, shortage of drugs and insulin and lack of diabetes care team were the major factors behind those serious issues of diabetic control and complications." (PMID 26879899, 2016). "First, insulin resistance is thought to be a key factor in the development of diabetes; unfortunately, insulin did not appear in a large number of studies outcomes." (PMID 27347994, 2016). "Regardless of etiology, all forms of diabetes are characterized by either absolute or relative defects in insulin secretion." (PMID 27558530, 2016). "Banerjee and Chakraborti (2014) have shown that glyoxal, a highly reactive oxoaldehyde, is elevated in diabetes and modifies Lys145 (a residue within one of two Mb CRAC/CARC motifs), suggesting that insulin may also effect Mb function." (PMID 27656147, 2016). "For people from a South Asian background, diabetes and insulin were viewed in very negative terms, and it was expressed that they were not culturally accepted." (PMID 27230479, 2016). "Patients with DR also had a longer diabetes duration, were more frequently treated with insulin, and had higher HbA1c concentrations than patients without DR." (PMID 27274760, 2016). "Increased diabetes prevalence in the group receiving TMP-SMX prophylaxis can most likely be explained by the more frequently administration of tacrolimus, which has decreased insulin sensitivity as a common side effect." (PMID 26912326, 2016). "The present study revealed a significant increase in serum FGF23 levels in normoglycemic individuals with a first-degree FHD, accompanied by increases in serum insulin levels and HOMA-IR values, and these findings are consistent with those of most studies of diabetes populations." (PMID 27698482, 2016). "Diabetes mellitus (DM) comprises a group of metabolic diseases resulting in hyperglycemia, either because the body does not produce enough insulin, or cells do not respond to the insulin that is produced or both." (PMID 26879899, 2016). "Among the 160 TB patients who knew their diabetes status, 12 (7.5%) were not engaged in any type of intervention such as exercise, diet change, or medicine (tablet, insulin) to control their diabetes." (PMID 27798659, 2016). "GHRHR antagonists may target certain complications of diabetes, especially in Type 1 diabetes and insulin-dependent T2DM, where insulin production by the beta-cell is at least clinically insignificant." (PMID 27777568, 2016). "The Women’s Health and Ageing Study II demonstrated dysregulation of blood glucose and insulin in response to oral glucose tolerance test in 73 community dwelling women aged 84–95 years not known to have diabetes." (PMID 28031949, 2016). "The clinical and biochemical findings of patients with T1DM revealed no significant gender difference in diabetes duration, daily insulin dose, BMI, SBP, DBP, HbA1c, and lipid profile." (PMID 27353561, 2016). "“Late stage” diabetes, LT2D, will finally occur when a total destruction of the pancreatic beta cells leads to a complete cessation of insulin secretion and the patients become dependent on regular insulin injections in addition to metformin." (PMID 26877773, 2016). "While the role of miR-450a on the regulation of endocrine function or in diabetes is not clear to date, miR-185 plays an important role in the regulation of insulin secretion and β cell growth via targeting suppressor of cytokine signaling 3 (SOCS3)." (PMID 27153060, 2016). "During the development of the type 2 diabetes mellitus rat model, the changes in hypothalamic NPY contents and its correlation with the insulin, leptin, and ghrelin levels, as well as the potential mechanism underlying their interactions have not yet been reported." (PMID 27867820, 2016). "Overall, regardless of the severity of diabetes, vanadium therapy needs a minimum level of plasma insulin, secreted endogenously, or received exogenously." (PMID 26459400, 2016).
diabetes (continued). "Type 2-diabetes, previously termed non-insulin dependent diabetes mellitus (NIDDM) or adult-onset diabetes, is characterized by progressive destruction of islet β-cells, resulting in decreased insulin production and decreased action of insulin on peripheral tissues." (PMID 26961231, 2016). "The inability to achieve satisfactory clinical control of canine diabetes without administration of exogenous insulin indicates that this is an insulin-dependent disease." (PMID 27031512, 2016). "The atherosclerosis risk in communities study reported weak, inverse cross-sectional associations between fasting glucose and insulin quintiles with RMSSD and RR among people without diabetes." (PMID 26983644, 2016). "STZ-induced diabetes significantly reduced serum insulin levels, and increased kidney weight, urinary glucose and protein levels compared to controls rats without diabetes (C) at the 8th week." (PMID 27901066, 2016). "This suggests that residual insulin action, likely originating from STZ-escaping β-cells, is still present after STZ administration in Gcgr-/- animals, and is necessary to prevent hyperglycemia and diabetes." (PMID 27092792, 2016). "Animals without IRS-2 exhibited insulin resistance with fasting hyperglycemia, due to inadequate insulin production, which in final resulted in diabetes, which was worse than lack of IRS-1." (PMID 27413253, 2016). "In healthy subjects but not those with diabetes, the physiologic insulin release will have stabilised postprandial glycaemia and returned it to the baseline level by 120 min and therefore longer test sessions are unnecessary." (PMID 27070641, 2016). "In general, type 1 diabetes patients meeting the TM and CAM were older, had a longer diabetes duration and a slightly longer duration of insulin therapy than those neither meeting the TM nor the CAM." (PMID 27553193, 2016). "Impaired insulin secretion has been examined in 2,324 Japanese men and 1,472 Japanese women without diabetes (age 30–79 years)." (PMID 27612202, 2016). "Diabetes mellitus manifests with hyperglycemias due to the lack of insulin secretion or defects of insulin action upon its receptors, or both." (PMID 27974933, 2016). "These individuals were older, more likely to be on insulin, and more likely to have diabetes complications than those without secondary care evidence of diabetes, as anticipated." (PMID 27631769, 2016). "When BMI was not included in the regression analysis, both insulin and diabetes showed significantly negative relationships with NAART, suggesting that BMI, insulin and diabetes influenced the outcome of verbal IQ through a probable common pathway." (PMID 27642517, 2016). "Diabetes is a disease in which the body does not sufficiently produce and/or respond to insulin, a pancreatic endocrine hormone crucial for maintaining glucose homeostasis." (PMID 27110686, 2016). "Diabetes is due to either the pancreas not producing enough insulin or the cells of the body not responding properly to the insulin produced." (PMID 27273319, 2016). "Diabetes with complications needs more than one OHA with or without insulin to maintain glycaemic control." (PMID 27195294, 2016). "T2DM can be further divided into Insulin-Treated Diabetes Mellitus (ITDM) (requiring insulin therapy with or without oral hypoglycemic medications as treatment) and non-ITDM (require only diet control and oral hypoglycemic agents as treatment)." (PMID 27111304, 2016). "Interestingly, acute parasite infection in DIO+I induced a high insulin secretion which was able to maintain near to normal glucose levels, but during the chronic phase of infection, hyperglycemia was accompanied by low insulin levels, which may result in a progression to diabetes." (PMID 26921251, 2016). "They included some with intractable epilepsy who had not found a treatment that worked, and some with diabetes who had regularly abused their insulin while also having an eating disorder." (PMID 26140336, 2016).